EGFR (epidermal growth factor receptor)
Diseases named in the same sentence as EGFR in open-access papers (continued):
Sharing a sentence is not in itself a finding about the gene and the disease.
lung cancer (continued). "Point mutations in EGFR are frequently found in patients with lung cancer of this type, and those known to activate EGFR include L858R and T790M." (PMID 35668076, 2022). "Epidermal growth factor receptor (EGFR) tyrosine kinase inhibitors (TKIs) have been widely used for EGFR mutation lung cancer patients." (PMID 35365136, 2022). "A total of 212 newly diagnosed lung cancer patient biopsy and resection specimens from primary and metastatic sites were tested to identify the type and number of EGFR mutations along with their molecular and clinical characteristics." (PMID 36613084, 2022). "This study aimed to determine the association between TMB and treatment outcomes in patients with epidermal growth factor receptor (EGFR)-mutated lung cancer that were treated with tyrosine kinase inhibitors (TKIs)." (PMID 36140210, 2022). "Activating EGFR mutations are common in lung cancers and can be treated by EGFR‐TKIs such as erlotinib and gefitinib." (PMID 35603909, 2022). "Tyrosine kinase inhibitors (TKIs) that target epidermal growth factor receptor (EGFR) mutations are commonly administered to EGFR-positive lung cancer patients." (PMID 36530971, 2022). "Athymic nude mice were injected with H1975 human lung cancer cells (5 × 106), expressing the EGFR T790M mutation which confers resistance to erlotinib (EGFR-TKI), in their flank and administered UA (25 mg/kg) via daily injection for 18 days." (PMID 36364289, 2022). "Patients with non–small cell lung cancer (NSCLC) with activating mutations in the epidermal growth factor receptor (EGFR) clearly benefit from EGFR–tyrosine kinase inhibitor (EGFR-TKI) therapy." (PMID 36048538, 2022). "Further investigation is needed to illustrate the complex relationship between the EGFR Q787Q polymorphism and lung cancer pathophysiology." (PMID 35387120, 2022). "Activation of TDO and elevated secretion of Kyn in CAFs isolated from NSCLC patients revealed that CAFs are closely linked to the lung cancer cells proliferation and EGFR TKIs resistance." (PMID 35831824, 2022). "Lung cancer is frequently caused by activating mutations in the epidermal growth factor receptor (EGFR)." (PMID 35534503, 2022). "Our findings reveal the importance of EGFR mutation analysis in individual tumors of multiple primary lung cancers." (PMID 35740676, 2022). "A series of studies have found that first- and second-generation TKIs have achieved improved progression-free survival (PFS) than platinum-based doublet chemotherapy in EGFR-mutated advanced lung cancer." (PMID 35571073, 2022). "A significant proportion of lung cancer patients show epidermal growth factor receptor (EGFR) mutation status discordance between the primary cancer and the corresponding brain metastases, which can affect prognosis and therapeutic decision-making." (PMID 35912248, 2022). "The EGFR mutation L858R expression and exon 19 in-frame deletion are correlated to a higher sensitivity of lung cancer to EGFR tyrosine kinase inhibitors." (PMID 36011604, 2022). "We found that a short treatment with afatinib caused an acute upregulation of FGF1 in EGFR mutant lung cancer cells." (PMID 35840561, 2022). "The purpose of this review is to summarize current literature, opportunities, and challenges for liquid biopsy and PGx testing as precision therapy tools in the management of EGFR mutated lung cancer." (PMID 35209919, 2022). "It has been shown in several studies that the epidermal growth factor receptor (EGFR) mutations-targeted treatment has made encouraging achievements in lung cancer." (PMID 36568152, 2022). "Except in a few cases, tumors with EGFR or ALK mutations showed a linear connection between 22C3 and SP263, which is likely attributable to high levels of PD-L1 expression in lung cancer samples with driver mutations like EGFR or ALK mutations." (PMID 35804910, 2022). "Lung cancers with a mutated epidermal growth factor receptor (EGFR) are a major contributor to cancer fatalities globally." (PMID 36344580, 2022).
lung cancer (continued). "A recent study using proteomic analysis observed potential tyrosine kinase inhibitor (OSM) sensitivity indicators in EGFR-mutated lung cancer and identified novel targets for future therapy options." (PMID 35745729, 2022). "For lung cancers, lung adenocarcinomas baring mutations in EGFR, KRAS, ERBB2, and MET are reported to also host a higher number of “rearrangements”34." (PMID 35710642, 2022). "A preclinical investigation indicated that pemetrexed treatment overcomes acquired resistance to gefitinib in EGFR-mutated lung cancer cells." (PMID 36553449, 2022). "Identification of EGFR gene mutations in lung cancer cells is important because certain types of EGFR gene mutations confer resistance to EGFR-TKIs, and the choice of EGFR-TKIs treatment is determined by the type of EGFR gene mutation." (PMID 35664805, 2022). "This pilot study has prospectively enrolled a total of 10 patients who were newly diagnosed with advanced stage III or IV lung cancers, and had tested for tissue EGFR mutation." (PMID 36256645, 2022). "Do patients with EGFR mutation-positive early-stage lung cancer require postoperative adjuvant targeted therapy?" (PMID 36304772, 2022). "The results showed that DEmRNAs participating in the networks were enriched in pathways associated with ‘cancer’ and ‘EGFR signaling’, which are related to lung cancer." (PMID 36091160, 2022). "EGFR mutations represent the second most common oncogenic driver event in lung cancer and accounts for ~15–20% of lung adenocarcinoma cases, while EGFR mutations are rare in other NSCLC subtypes." (PMID 35053553, 2022). "Non‐invasive saliva‐based EGFR gene mutation and activated EGFR signalling pathway had been tested in patients with lung cancer." (PMID 36448260, 2022). "In this study, the total mutation rate of the EGFR gene in the lung cancer patients of East Yunnan Province was noted to be 47.22%, the highest mutation rate in the tissue samples was 53.40%, and the mutation rate in adenocarcinoma patients was 49.67%." (PMID 35606799, 2022). "Compared with EGFR TKI alone, the combination of BA and EGFR TKI demonstrated promising efficacy against EGFR-TKI-resistant lung cancer cells and was associated with inducing cytotoxic autophagy." (PMID 36358919, 2022). "As is known, EGFR, related to cell proliferation and survival, plays an important role in the progression of lung cancer and is easily mutated." (PMID 34766737, 2022). "TMB, CIS, and MATH scores help to evaluate intratumor genetic heterogeneity, which is closely related to drug resistance and poor outcomes in patients with lung cancer harboring EGFR mutations." (PMID 35029047, 2022). "We herein present the first case report of lung cancer with the co-occurrence of uncommon and complex EGFR (L858R and E709X) and CTNNB1 mutations that was successfully treated with afatinib." (PMID 36519636, 2022). "Somatic activating mutations in EGFR are the most common oncogenic driver in non‐small cell lung cancer (NSCLC), which have benefited from EGFR‐targeting therapies." (PMID 35543090, 2022). "Afatinib has been approved for patients with lung cancer carrying uncommon epidermal growth factor receptor gene (EGFR) mutations." (PMID 36358728, 2022). "The discovery of somatic activating mutations in the epidermal growth factor receptor (EGFR) associated with dramatic responses to tyrosine kinase inhibitor (TKI) treatment resulted in precision medicine in the field of lung cancer therapeutics." (PMID 36553449, 2022). "Overall, these results implicated the therapeutic potential of AhR inhibitors in EGFR-associated lung cancer." (PMID 35831824, 2022). "EGFR mutations are frequently observed in lung cancers and related to shorter progression-free survival." (PMID 35269825, 2022). "In lung cancer, using CT images to train deep learning models and predict EGFR mutations has been studied and shows promising performance." (PMID 36300191, 2022).
lung cancer (continued). "In this study, we reported that EGFR mutation-containing lung cancer cells produced CLEC11A with endothelial trophic and tumor-promoting activities." (PMID 35267664, 2022). "Treatment of advanced-stage lung cancer has dramatically changed since the discovery of the EGFR gene mutation in the 2000s and various driver gene mutations." (PMID 36100844, 2022). "We demonstrated that it is feasible to apply a multi-sequence radiomic model to noninvasively predict the EGFR mutation status of lung cancer BMs." (PMID 35912248, 2022). "VEGF expression can be upregulated in EGFR-mutant lung cancers, which is the underlying mechanism for enhancing the sensitivity of EGFR-mutant patients to bevacizumab or ramucirumab." (PMID 35884533, 2022). "They showed that activated NF-κB promotes the expression of AICDA, which induces the deamination of 5-methylcytosine to thymine at position 2369 and generates the EGFR T790M mutation in lung cancer cell lines." (PMID 35740609, 2022). "NSCLC comprises of 85% of lung cancer cases and is characterized by diverse gene mutations, including epidermal growth factor receptor (EGFR), B-Raf oncogene (B-RAF), and anaplastic lymphoma kinase (ALK)." (PMID 35745617, 2022). "We aim to identify novel genetic alterations associated with drug resistance in lung cancer and colorectal cancer patients who were treated with EGFR-targeted therapy and cytotoxic chemotherapy through whole exome sequencing (WES) of cfDNA." (PMID 35402275, 2022). "employed liquid biopsy technology to detect EGFR mutations in the CSF of lung cancer patients with BPM or LM." (PMID 36601482, 2022). "The results of this study provided an optimal treatment strategy for EGFR‐mutated non‐small cell lung cancer patients with brain metastasis." (PMID 35394114, 2022). "RTKs are important components of the cellular signaling apparatus and are frequently mutated or otherwise dysregulated in NSCLC, such as EGFR, the classical driver of lung cancer." (PMID 38091511, 2022). "In subsequent studies, scientists successfully detected EGFR‐L858R and EGFR‐T790 M mutations in DNA fragments derived from non‐small cell lung cancer (NSCLC) patients." (PMID 35845351, 2022). "Ror1 is upregulated in lung cancer and has been associated with resistance to Tyrosine Kinase Inhibitor (TKIs) therapy in epidermal growth factor receptor (EGFR) positive NSCLC." (PMID 35742983, 2022). "EGFR signaling is associated with the malignant behaviors of lung cancer and drives uncontrolled cell growth and invasion." (PMID 35090513, 2022). "EGFR is a significant target for lung cancer diagnosis and treatment; thus, non-invasive, accurate, and rapid methods for EGFR mutation detection should be developed in NSCLC." (PMID 36276079, 2022). "Kirsten rat sarcoma viral oncogene homolog (KRAS) is the most common oncogenic driver in solid tumors including lung cancer and was associated with a worse prognosis and resistance to chemotherapy and anti-epidermal growth factor receptor (EGFR) treatment." (PMID 36230855, 2022). "Several other lnRNAs such as BC087858, metastasis associated lung adenocarcinoma transcript 1 (MALAT-1) have been implicated in the promotion of EGFR TKIs resistance in lung cancer via regulation of EMT process." (PMID 35209919, 2022). "Nevertheless, the current research is incapable of clearly illustrating the underlying mechanisms relating to dysregulated ncRNAs in EGFR TKI-resistant lung cancer." (PMID 36139582, 2022). "The severe ADR was a central retinal artery thrombosis in a patient undergoing treatment with gefitinib for EGFR-mutated non–small cell lung cancer, causing blindness in the affected eye." (PMID 35641217, 2022). "As the most common driver mutation in lung cancer, we emphatically analyzed the subgroup of EGFR-mutant NSCLC." (PMID 36123526, 2022). "Nevertheless, ICI efficacy in patients with lung cancer harboring EGFR mutations is limited on the basis of prospective trials and a registry trial." (PMID 36082280, 2022).
lung cancer (continued). "EGFR tyrosine kinase inhibitors (TKIs) have greatly improved the prognosis of non‐small cell lung cancer (NSCLC) patients with EGFR‐TKI sensitizing mutations over traditional platinum‐based chemotherapy." (PMID 35593080, 2022). "The primary objective of this work was to analyze the presence of EGFR mutations in cfDNA of 86 patients with lung cancer undergoing oncological treatment related to response to treatment with TKIs." (PMID 35884384, 2022). "The second-generation of EGFR tyrosine kinase inhibitors, such as afatinib and dacomitinib, are effective against EGFR-mutated breast and lung cancer, but ineffective against T790M-mutated cancer." (PMID 36457709, 2022). "The common drivers of lung cancer, such as EGFR mutations and ALK rearrangement, are rarely detected in pLELC, indicating that the key carcinogens of LELC are not tobacco exposure or somatic cell driver mutations." (PMID 35237520, 2022). "In this study, the EGFR mutation status in multiple primary lung cancers was examined, and its discordance rate in individual tumors was determined to be high." (PMID 35740676, 2022). "ddPCR is an accurate and rapid method for the detection of EGFR mutations with clinical utility for patients with advanced lung cancer." (PMID 35202431, 2022). "For EGFR mutations, generations of TKIs were developed and were used in the treatment of lung cancer." (PMID 35514980, 2022). "Several studies showed promising results of radiomics in the detection of EGFR mutation and survival prediction in patients with advanced lung cancer treated with EGFR TKIs." (PMID 35875167, 2022). "The incidence of LM in patients with lung cancer, especially in patients with EGFR mutations, is increasing with the emergence of new targeted drugs." (PMID 35287683, 2022). "Activation of the RAS-MAPK signaling pathway is a common mechanism of osimertinib resistance in KRAS-mutated lung cancer cells and EGFR-TKI-resistant cells." (PMID 36712673, 2022). "Patients with lung cancer harboring drug-sensitive mutations on the EGFR gene, such as exon 19 deletion or exon 21 L858R mutations, show dramatic and durable responses to EGFR-TKIs." (PMID 35326664, 2022). "In practice, a few ncRNAs derived from drug-resistant-mutated lung cancer cells have been found to facilitate EGFR TKI resistance." (PMID 36139582, 2022). "Lung cancer with EGFR gene mutations has been observed in over 15% of NSCLC adenocarcinomas, with a frequency of around 62 percent in Asian populations." (PMID 35745729, 2022). "Although EGFR inhibitors have represented a turning point in the treatment of EGFR-mutated lung cancer, most stage IV patients will suffer from disease progression and eventually die from it." (PMID 36727053, 2022). "EGFR mutation‐positive lung cancer patients, for example, were found to not only be unresponsive to PD‐1/PD‐L1 inhibition but even to hyper‐progress after immunotherapy." (PMID 34898004, 2022). "In this study, we compared the prevalence of EGFR Q787Q polymorphism between the general and lung cancer populations." (PMID 35387120, 2022). "A previous study reported that high expression of MCTS1 induced the generation of ROS, which caused YY-1/EGFR/MnSOD signaling amplification and cancer cell invasion in lung cancer." (PMID 35295953, 2022). "In conclusion, this is the first study based on STMs to predict the molecular features of EGFR‐mutated lung cancer during the targeted therapy, including clearance of targeted EGFR ctDNA and the emergence of secondary EGFR T790M." (PMID 35543090, 2022). "Overactivation or gain-of-function mutation of EGFR are prevalent in a variety of epithelial cancers (e.g. breast and lung cancers)." (PMID 35410300, 2022). "EGFR germline mutations, including the mutations p.T790M and p.R776H in exon 20 and p.V843I in exon 21, are associated with genetic susceptibility to lung cancer." (PMID 35320498, 2022).
lung cancer (continued). "As 1 paradigm-defining example of precision medicine, activating mutations in the EGFR are associated with high response rates to EGFR-directed tyrosine kinase inhibitors (TKIs) in non–small cell lung cancer (NSCLC)." (PMID 35579943, 2022). "In NSCLC, the majority of patients with Ex20ins are resistant to first- and second-generation EGFR TKIs, in contrast to lung cancers with Ex19del or L858R mutations." (PMID 35053553, 2022). "Patients with a second primary lung cancer were less likely to have pGGNs and more likely to have sGGNs, and those with EGFR mutations exhibited a similar trend (P = 0.05)." (PMID 36313724, 2022). "The EGFR mutation occurs in 10–20% of patients with lung cancer (80–85% of NSCLC) and is mostly adenocarcinoma in younger women and never-smokers." (PMID 35330479, 2022). "The effects on cell viability and clonogenic capacity by icotinib were detected in EGFR- mutated lung cancer." (PMID 35690866, 2022). "From our research, we collected 78 lung cancer serum samples; among them, 30 are EGFR mutation samples; it is hard to explore the relationship between EGFR mutation and CAP1 expression with limited sample size." (PMID 34636991, 2022). "EGFR tyrosine kinase inhibitors treatment was the main strategy for patients diagnosed with lung cancer harbouring EGFR mutations, however, acquired drug resistance limited the treatment efficiency." (PMID 36336787, 2022). "This diagnostic testing strategy will have to be modified as osimertinib becomes a first line modality for EGFR-mutated lung cancers, leading to different mechanisms of therapeutic resistance." (PMID 35202431, 2022). "The EGFR gene mutation profile of the lung cancer patients of coal-producing areas in Eastern Yunnan was found to be remarkably different from that of non-coal-producing regions." (PMID 35606799, 2022). "The most frequent mechanism of acquired resistance to first- and second-generation EGFR-TKIs in EGFR-mutated lung cancer is the presence of an EGFR T790M mutation in exon 20 and confers sensitivity to third-generation inhibitors." (PMID 36497340, 2022). "By applying walker DNA to a catalytic hairpin assembly and using the differential dispersibility of gold nanoparticles, we detected EGFR exon 19 deletion mutant #2 DNA associated with lung cancer." (PMID 35591635, 2022). "EMT is implicated in mediating resistance to EGFR inhibitors, chemotherapy, and other targeted drugs in lung cancer." (PMID 35874749, 2022). "EGFR mutation is one of the most common genotypes of lung cancer and occurs in at least 50% of NSCLC in Asia." (PMID 35814445, 2022). "In lung cancer, the TK activity is frequently dysregulated by several oncogenic mechanisms, including EGFR gene mutation, EGFR gene copy number alternation and overexpression of EGFR protein." (PMID 35494059, 2022). "Molecular analysis of epidermal growth factor receptor (EGFR) mutations in individual tumors of multiple lung cancers is essential for devising an optimal therapeutic strategy." (PMID 35740676, 2022). "The detailed characteristics of EGFR gene mutations in the lung cancer patients in other coal-producing areas in Eastern Yunnan are still unclear." (PMID 35606799, 2022). "Lung cancer patients with different EGFR gene mutations can experience a differential effect of the treatment." (PMID 35606799, 2022). "Studies have found that personalized treatments with genotype-directed therapies targeted to lung cancer patients with EGFR mutations can significantly improve their survival and quality of life." (PMID 36248421, 2022). "In particular, several hotspot mutations of EGFR which are implicated in non–small cell lung cancer, were discovered to co-occur in cis with other EGFR mutations." (PMID 36860695, 2022).